GAL (galanin and GMAP prepropeptide)
Description:
Endocrine hormone of the central and peripheral nervous systems that binds and activates the G protein-coupled receptors GALR1, GALR2, and GALR3. This small neuropeptide may regulate diverse physiologic functions including contraction of smooth muscle of the gastrointestinal and genitourinary tract, growth hormone and insulin release and adrenal secretion.
Synonyms: GMAP; GALN; GLNN; GAL-GMAP; ETL8
Tractability: Small molecule: a structure with a bound ligand is known. Antibody: UniProt places it where antibodies can reach, with high confidence; its Gene Ontology location is reachable by antibodies, with high confidence; UniProt predicts a signal peptide or a membrane-spanning region.
Safety:
Unwanted effects reported when the protein is acted on. In parentheses: how it was acted on, where the effect was seen, and who reports it.
heroin dependence (source: ClinPGx)
Gene: Protein-coding gene on chromosome 11 (68,683,020 to 68,691,205, forward strand). Ensembl gene ENSG00000069482.
Subcellular location: Secreted
Subcellular location (Human Protein Atlas): Golgi apparatus; Vesicles; Predicted to be secreted
Pathways (Reactome):
Signal Transduction: G alpha (i) signalling events; Peptide ligand-binding receptors
Gene Ontology:
Molecular function: galanin receptor activity; neuropeptide hormone activity; protein binding; type 1 galanin receptor binding; type 2 galanin receptor binding; type 3 galanin receptor binding; galanin receptor binding; hormone activity
Biological process: adenylate cyclase-activating G protein-coupled receptor signaling pathway; positive regulation of cortisol secretion; positive regulation of timing of catagen; positive regulation of transcription by RNA polymerase II; signal transduction; insulin secretion; neuropeptide signaling pathway; behavioral response to ethanol; drinking behavior; feeding behavior; locomotory behavior; negative regulation of cell population proliferation; negative regulation of lymphocyte proliferation; positive regulation of apoptotic process; regulation of glucocorticoid metabolic process; response to estrogen; response to immobilization stress; response to insulin; response to peptide; response to xenobiotic stimulus
Cellular component: extracellular region; neuronal cell body; secretory granule
Genetic constraint (gnomAD): Loss-of-function variants: 5 observed, 5.61 expected, observed/expected ratio (o/e) 0.89, 90% interval 0.46 to 1.72. That is too few expected variants to judge how well the gene tolerates losing a copy. Missense variants: 26 observed, 23.48 expected, observed/expected ratio (o/e) 1.11, 90% interval 0.81 to 1.53. Synonymous variants: 16 observed, 11.19 expected, observed/expected ratio (o/e) 1.43, 90% interval 0.95 to 1.9.
Homologues: Orthologues: chimpanzee GAL (99% identical), pig GAL (73% identical), mouse Gal (71% identical), guinea pig GAL (67% identical), macaque GAL (67% identical), dog GAL (66% identical), rat Gal (62% identical), zebrafish gal (49% identical).
Diseases named in the same sentence as GAL in open-access papers:
GAL is named in the same sentence as 177 diseases in open-access papers, as found by Europe PMC text mining. Sharing a sentence is not in itself a finding about the gene and the disease. The quoted sentences say what the papers report.
depression (22 papers, 2013 to 2026). "While GAL rs948854 and rs4432027 SNPs were found to associate with anxiety, the rs1042577 SNP was significantly associated with both anxiety and depression." (PMID 31881033, 2019). "Genetic association analyses of six GAL single nucleotide polymorphisms with anxiety and depression have been carried out with one-way analyses of covariance in an allele-wise method." (PMID 31881033, 2019). "It has been demonstrated that GAL system is associated with major depression in a postmortem brain study." (PMID 30487761, 2018). "This study aimed to investigate the association of galanin (GAL) gene and the development of depression in the Chinese Han population." (PMID 23741354, 2013). "The findings clearly indicate that the GAL gene polymorphism is closely correlated to the incidence of depression in the Chinese Han female patients." (PMID 23741354, 2013). "A series of statistical methods were carried out to investigate the correlation between the GAL gene SNP and the patient susceptibility to depression." (PMID 23741354, 2013). "This study investigated the relationship between the GAL gene SNP and the susceptibility to depression in the Chinese Han population." (PMID 23741354, 2013). "Interestingly, in humans, certain gene variants of GAL and their receptors confer vulnerability towards psychosocial stress and increase the risk of developing anxiety and depression." (PMID 35692389, 2022). "In contrast to former research aimed to find genetic associations between GAL gene variants and mood characteristics in subjects with clinical anxiety and depression [, the novelty of the present study is that it was performed on a cohort of apparently normal, healthy volunteers." (PMID 31881033, 2019). "Similar results have been also demonstrated in two other independent studies of depression and panic disorders in Sweden, in which the GAL gene polymorphism site of rs948854 showed a high degree of correlation with the severity of symptoms of female patients with depression." (PMID 23741354, 2013). "Although different SNP sites in GAL were reported in these studies, all these observations suggest a positive correlation between the GAL gene polymorphism and the susceptibility of female patients to depression." (PMID 23741354, 2013). "A genome-wide screening study showed sharp associations in SNPs (rs2156464) between the GAL gene and major depression and SNPs (rs948854) associated with both anxiety disorder, MDD, and HPA axis overactivity in female patients." (PMID 41009573, 2025). "Therefore, species or race-associated differences may, at least partially, explain why depression is correlated with SNPs of rs694066 in GAL in Chinese Han women but with GAL SNPs of rs948854 in Swedish women." (PMID 23741354, 2013). "GAL and its receptors can also interact with noradrenaline, neuropeptide Y, brain-derived neurotrophic factor, and dopamine to regulate depression." (PMID 40048451, 2025). "The role of GAL in depression has been studied using animal models and behavioural tests such as the forced swimming test (FST), a widely validated test for the study of the effects of antidepressants, and in animal genetic models." (PMID 39484753, 2025). "A study conducted on an FST rat model of depression showed that exposure to stressors induce the release of GAL but the effect on its receptors varies." (PMID 36829752, 2023). "Similar to how it affects depression, GAL’s impact on anxiety is dependent on the receptor it is acting on." (PMID 36829752, 2023). "Further, SPX and GAL are also involved in depression and anxiety, where studies in fish have shown a possible anxiolytic function of SPX." (PMID 35692389, 2022). "Studies have shown the effects of galanin on anxiety and depression; however, a correlation between depression and plasma levels of GAL proved positive only in women." (PMID 36004833, 2022).
depression (continued). "In the central nervous system, GAL is co-expressed with serotonin and norepinephrine, of which both are involved in depressive disorder." (PMID 36004833, 2022). "Neuropeptides, such as neuropeptide Y (NPY), substance P, and galanin (GAL), were found to be affected by stress or to be involved in stress response, in some animal models or human depression patients." (PMID 33100903, 2020). "It has been demonstrated that GAL system plays an important role in depression, and drugs that target galanin receptors can modulate stress-related behaviors." (PMID 30487761, 2018). "Thus, it is likely that GAL has a crucial role in developing depression, particularly if a person experiences childhood trauma or recently experienced negative events." (PMID 35692389, 2022). "In rodents, there is a clear involvement of GAL in anxiety and depression." (PMID 35692389, 2022). "In addition, SPX and GAL have roles in modulating serotonin activity, indicating roles in mood disorders such as anxiety and depression." (PMID 35692389, 2022). "Given the proactive role played by GAL and its receptor in depression/anxiety; the role of spexin in depression can be speculated." (PMID 32376994, 2020). "DNA methylation of GAL in the prefrontal cortex plays a role in major depressive disorder." (PMID 29682090, 2018). "All these pieces of evidence suggest that GAL may play an important role in the pathogenesis of depression." (PMID 23741354, 2013). "In conclusion, this study has demonstrated a positive correlation between the SNP site of rs694066 in the GAL gene and the susceptibility of the female but not male Chinese Han patients to depression." (PMID 23741354, 2013). "The expression of somatodendritic 5HT1a autoreceptors (significantly involved in the pathophysiology of major depression) in the DR nucleus may be modified by GAL with a consequent enhancement of serotonergic transmission." (PMID 23986909, 2013). "GAL, upon its action on its three GAL receptors (GALR1-3), participates in numerous physiological processes and different disease, including mood regulation and depression in animal models." (PMID 34639188, 2021).
Anxiety (14 papers, 2019 to 2026). Intense feelings of nervousness, tension, or panic often arise in response to interpersonal stresses. "Previous association studies in humans found SNPs around GAL associated with excess ethanol intake and anxiety in men." (PMID 40614114, 2025). "According to these results, the risk effect of the T allele of the GAL rs1042577 SNP for higher anxiety scores was present in both genders." (PMID 31881033, 2019). "Furthermore, a study conducted on 597 subjects who handed in their DNA samples showed a significant association between anxiety and the GAL rs948854_C–rs4432027_C haplotype and the rs1042577_T single-locus allele, respectively." (PMID 36829752, 2023). "Furthermore, on an EPM anxiety model of rats the intra-dorsal hippocampal administration of GAL caused anxiogenic effects, while the administration of GAL2R antagonist M871 had anxiolytic-like effects." (PMID 36829752, 2023). "Stress because of exposure to predator scent reduces GAL mRNA levels in the frontal cortex and hippocampus and induces anxiety-like behavior." (PMID 35692389, 2022). "In the present study, we submitted young and aged GAL2-KO and GAL3-KO mice to a spatial learning task and two anxiety-related behavioral tests to examine if the GAL system is involved in these cognitive functions and affected by aging." (PMID 33915732, 2021). "In mice, GAL mRNA is expressed at high levels in the amygdala, hypothalamus, locus coeruleus and the dentate gyrus of the hippocampus, which are crucial structures for the regulation of anxiety and stress." (PMID 33915732, 2021). "Finally, we conclude that the GAL neuropeptide system might be a promising target for the development of therapeutics which target age-related comorbidities such as anxiety or reduced memory function either as an antagonist (GAL2-R) or agonist (GAL3-R)." (PMID 33915732, 2021). "We showed that neuropeptide GAL signaling through GAL3-R is relevant for learning and anxiety in an age-dependent manner." (PMID 33915732, 2021).
Obesity (10 papers, 2016 to 2022). Accumulation of substantial excess body fat. "The results indicate that GAL is associated with lipid metabolism and glucose homeostasis in these children and suggest that GAL is involved in the development of obesity and associated metabolic disorders." (PMID 33802616, 2021). "It has been reported that modifications in pain threshold (antinociceptive and nociceptive) caused by obesity are modulated by GAL." (PMID 33802616, 2021). "In the case of celastrol, this pentacyclic triterpene exerts an anti-obesity action by suppressing GAL-induced fat intake and by activating the PGC-1α/glucose transporter 4 axis-mediated glucose consumption." (PMID 33802616, 2021). "Thin men and women display a lower plasma level of GAL than individuals with obesity, and the level of GAL in the serum is high in obese menopausal women, but this level is decreased in the cerebrospinal fluid of recovered anorexic women." (PMID 33802616, 2021). "In accordance with these pharmacological studies, transgenic mice with high levels of endogenous GAL develop obesity and alterations in lipid metabolism." (PMID 27550417, 2016). "GAL increases fat deposition and contributes to the development of obesity by favoring glucose utilization over fat utilization." (PMID 27550417, 2016). "In women with moderate/severe obesity a high plasma concentration of GAL has been reported." (PMID 33802616, 2021). "It must be clearly determined whether obesity increases the secretion of GAL and whether the GAL serum level could serve as a biomarker for the prediction of impaired glucose tolerance." (PMID 33802616, 2021). "The interaction between GAL and NPY in feeding and energy metabolism, the relationships between GAL and other substances involved in food intake mechanisms, the potential pharmacological strategies to treat food intake disorders and obesity and the possible clinical applications are discussed." (PMID 33802616, 2021). "This is also an important research line that must be developed in the future, since the level of GAL has been positively correlated with body fat (adiposity/obesity) and it seems that female puberty onset is mediated by steroids which stimulate GAL to increase fat intake." (PMID 33802616, 2021). "These increases in GAL+/VAChT+ nerve fibers could be a contributing factor to early onset diabetes and obesity in children and young adults who are exposed to BPA if the porcine models are an accurate depiction of human development, regardless of whether the dosage is legally acceptable or not." (PMID 29244763, 2017). "This might help to explain the putative role of GAL and these adipocytokines in obesity." (PMID 27550417, 2016). "In the present study, growth-related genes, GAL, CENPF, and GPC2, obesity-related gene, PEMT, and CYP3A4, P450, TMEM200B genes were found to be associated with BWF." (PMID 35795788, 2022). "Presented examples of regulatory role of ASTs clearly indicate their structural and functional homology with vertebrate GAL and SST, hormones which are closely connected with obesity." (PMID 34681728, 2021). "This is consistent with our analyses of GAL in the PVN, a neuropeptide that is positively related to a HFD and increased in a state of dietary obesity and, while unaffected by CXCL12 as shown here, is stimulated by another chemokine, CCL2." (PMID 27047354, 2016). "In the future, more understanding of the physiological effects of GAL and SPX with three GALRs could lead to the development of new therapeutic strategies such as neuroendocrine-based obesity elimination and reproductive abnormalities using GAL and SPX." (PMID 35692389, 2022). "This suggests that the augmented plasma level of GAL was due to obesity and not to food intake, and hence obesity increases the secretion of GAL." (PMID 33802616, 2021).
Obesity (continued). "Moreover, in the medial preoptic nucleus the level of GAL was positively correlated with body fat (adiposity) in female rats but not in males, and hence progesterone could play an important role in the development of obesity in females with a high-fat diet consumption." (PMID 33802616, 2021).
colitis (8 papers, 2014 to 2020). Inflammation of the colon. "The occurrence of GAL largely depends on the stage of the disease, e.g., in porcine experimental colitis GAL secretion is caused by infection with Brachyspira hyodysenteriae." (PMID 33552060, 2020). "Interestingly, the GAL administration to rats with acute colitis caused by TNBS resulted in a reduction in mucosal damage." (PMID 33013401, 2020). "Notably, the enhanced expression of GAL has been observed in animal models of inflammation, including proliferative enteropathy, chemically induced colitis, Salmonella infection, and gastritis caused by long-term aspirin administration." (PMID 27293908, 2016). "Similar upregulation of GAL synthesis has been observed in enteric neurons following formalin-induced porcine colitis." (PMID 24643520, 2014). "GAL plasticity within the enteric nervous system has been proven using various models of gastrointestinal damage, for example in the experimental model of formalin-induced colitis." (PMID 33013401, 2020). "The anti-inflammatory effect of GAL has been demonstrated in chronic TNBS-induced colitis." (PMID 33552060, 2020). "Similarly, expression of GAL was increased in the uterine perikarya in the Th10-S4 DRGs of gilts with uterine inflammation used in the present study and in the colon-projecting neurons in the CaMG of pigs with colitis." (PMID 32443879, 2020). "An increase in the population of GAL-LI neurons was observed in structures of the ENS, as well as extrinsic sources of innervation of the GI tract, following colitis, gastric ulcers, hyperacidity of the stomach, and enteric Salmonella infection." (PMID 31861419, 2019). "As a result of GAL administration, diarrhea decreased in acute TNBS-induced colitis in the rat." (PMID 33552060, 2020). "Inflammatory GAL induction in murine colitis is accompanied by parallel augmentation of GAL1 receptor expression in colonic epithelium, thus constituting a subsequent link of the GAL signaling pathway." (PMID 24643520, 2014).
diabetes (8 papers, 2016 to 2024). "The authors suggest that GAL levels decrease in the early stage of diabetes and increase in the later phase which is associated with organ regeneration." (PMID 33552060, 2020). "In porcine diabetes models, an increase in GAL-positive cells was observed after streptozotocin supplementation in antrum and pylorus but only in the myenteric plexus." (PMID 33552060, 2020). "Following diabetes induction, a significant increase in GAL expression in all parts of the small intestine was observed." (PMID 32192078, 2020). "Incorrect expression of GAL has been indicated in problems with energy metabolism in children, including diabetes mellitus." (PMID 29244763, 2017). "The three neural peptides (CART, CGRP, and GAL) have been correlated with childhood obesity and diabetes in several studies, previously cited." (PMID 29244763, 2017). "A study on diabetes observed that GAL contributed to the maintenance of glucose level homeostasis, could increase NO secretion, and inhibit ACh secretion." (PMID 39064711, 2024).